HIPK4 (homeodomain interacting protein kinase 4)
Description:
May act as a corepressor of transcription factors (Potential).
Synonyms: FLJ32818
Tractability: Small molecule: a high-quality ligand is known; it belongs to a druggable protein family. PROTAC: ubiquitination databases record sites on it; a small molecule that binds it is known.
Target class: CMGC protein kinase group; CMGC protein kinase HIPK subfamily; Enzyme; Kinase; CMGC protein kinase DYRK family; Protein Kinase
Gene: Protein-coding gene on chromosome 19 (40,379,271 to 40,390,181, reverse strand). Ensembl gene ENSG00000160396.
Subcellular location: Cytoplasm
Gene Ontology:
Molecular function: protein binding; ATP binding; histone kinase activity; protein kinase activity; protein serine kinase activity; protein serine/threonine kinase activity
Biological process: chromatin remodeling
Cellular component: cytoplasm; nucleus
Genetic constraint (gnomAD): Loss-of-function variants: 28 observed, 47.38 expected, observed/expected ratio (o/e) 0.59, 90% interval 0.44 to 0.81. The upper end of that interval is the gene's LOEUF score, 0.81, which puts it in group 3 of 6, group 1 being the genes least tolerant of losing a copy. Missense variants: 729 observed, 874.2 expected, observed/expected ratio (o/e) 0.83, 90% interval 0.78 to 0.89. Synonymous variants: 340 observed, 361.34 expected, observed/expected ratio (o/e) 0.94, 90% interval 0.86 to 1.03.
Homologues: Orthologues: chimpanzee HIPK4 (98% identical), macaque HIPK4 (97% identical), pig HIPK4 (91% identical), dog HIPK4 (89% identical), rabbit HIPK4 (89% identical), mouse Hipk4 (87% identical), rat Hipk4 (87% identical), guinea pig HIPK4 (85% identical), Drosophila melanogaster mnb (20% identical), Drosophila melanogaster Dyrk3 (19% identical), Caenorhabditis elegans mbk-1 (19% identical), Caenorhabditis elegans mbk-2 (17% identical), and 2 more. Paralogues in human: HIPK2 (38% identical), HIPK1 (38% identical), HIPK3 (38% identical), DYRK1B (21% identical), DYRK1A (21% identical), DYRK4 (19% identical), DYRK2 (19% identical), DYRK3 (19% identical), CLK1 (16% identical), CLK2 (16% identical), CLK3 (16% identical), CLK4 (15% identical).
Diseases named in the same sentence as HIPK4 in open-access papers:
HIPK4 is named in the same sentence as 12 diseases in open-access papers, as found by Europe PMC text mining. Sharing a sentence is not in itself a finding about the gene and the disease. The quoted sentences say what the papers report.
bladder cancer (1 paper, 2024). "Notably, the anticipated lower cytotoxicity of IMT is attributed to the observed lower expression levels of its primary targets, HIPK4 and SLC22A2, in bladder cancer compared to the targets of GCB and 5-FU." (PMID 38399266, 2024). "This projection stems from the observation that the primary targets for IMT (HIPK4 and SLC22A2) are not expressed as significantly in bladder cancer compared to the targets of GCB and 5-FU." (PMID 38399266, 2024).
Infertility (1 paper, 2023). "With HIPK4, expression is predominant, but not exclusive, to the testis of mice and humans (GTEx Portal), and genetic knockout leads to infertility due to reduced sperm production, impaired sperm motility, and abnormal head as well as tail morphogenesis." (PMID 37069147, 2023).
oligoasthenoteratozoospermia (1 paper, 2020). A form of male infertility that is characterized by a combination of low number or oligozoospermia, poor motility or asthenozoospermia, and abnormal shape or teratozoospermia of sperms. "HIPK4 is predominantly expressed in round and early elongating spermatids, and Hipk4 knockout males are sterile, exhibiting phenotypes consistent with oligoasthenoteratozoospermia." (PMID 32163033, 2020).
sterility (1 paper, 2020). "We postulate that the abnormal head structures of HIPK4-deficient sperm are a primary cause of sterility." (PMID 32163033, 2020). "Since HIPK4 expression is restricted to later steps of sperm development, HIPK4 inhibitors also would induce sterility more quickly than drugs that perturb earlier steps in spermatogenesis." (PMID 32163033, 2020).
infection (1 paper, 2020). The state of being infected such as from the introduction of a foreign agent such as serum, vaccine, antigenic substance or organism. "Untransduced fibroblasts or those expressing the K40S mutant maintained spindle-like morphologies, whereas cells expressing HIPK4 became either spherical or polygonal within two days after infection." (PMID 32163033, 2020).
tumor (1 paper, 2025). "Compared with that in the control group, the tumor weight and volume were significantly reduced in the HIPK4-knockdown group." (PMID 40316017, 2025). "Our preliminary experiment showed that HIPK4 was highly expressed in CSCC tumor tissues and cells." (PMID 40316017, 2025). "CSCC tumor tissues and adjacent tissues were collected from patients with CSCC, and we observed that HIPK4 and TAp63-pSer395 levels were significantly increased in CSCC tumor tissues compared with normal tissues, while EFEMP1 expression was reduced (n = 5)." (PMID 40316017, 2025). "Western blot results subsequently displayed that HIPK4 knockdown significantly reduced HIPK4, TAp63-pS395, Ki67, MMP2, and MMP9 levels, but elevated EFEMP1 levels in tumor tissues." (PMID 40316017, 2025). "To further study the effect of HIPK4 on CSCC malignant progression in vivo, we established a subcutaneous tumor model in nude mice." (PMID 40316017, 2025). "Our results showed that HIPK4 was highly expressed in CSCC, and its silencing inhibited CSCC cell malignant behaviors and tumor growth in CSCC-bearing nude mice, which was reported for the first time." (PMID 40316017, 2025). "In addition, HIPK4 was upregulated in CSCC; knocking down HIPK4 suppressed CSCC cell malignant behaviors and tumor growth in mice." (PMID 40316017, 2025). "Mechanistically, HIPK4 promoted tumor progression by phosphorylating the tumor suppressor TAp63 at Ser395, leading to decreased expression of EFEMP1, a key extracellular matrix protein with anti-tumor properties." (PMID 40316017, 2025).
HIPK4 also shares sentences with these, for which no sentence is quoted: cancer (2 papers); prostate tumor (2); cutaneous squamous cell carcinoma (1); Globozoospermia (1); leprosy (1); lung squamous cell carcinoma (1).